ERBB2 (erb-b2 receptor tyrosine kinase 2)
Diseases named in the same sentence as ERBB2 in open-access papers (continued):
Sharing a sentence is not in itself a finding about the gene and the disease.
cancer (continued). "Importantly, these are predictive biomarkers for drugs that are currently in use for treating different cancers, such as PARP, ERBB2, EGFR, PIK3CA, mTOR, and Hedgehog signaling inhibitors." (PMID 34575676, 2021). "On the other hand, it has been previously reported that EGF stimulation in cancer cells can promote both the homodimerization of EGFR and heterodimerization of EGFR with human epidermal growth factor receptor 2 (HER2)/Erb-B2 receptor tyrosine kinase 2 (ErbB2)." (PMID 33705793, 2021). "Drugs with targets such as EGFR, ERBB2, MTOR, PARP2, AURKB, MAP2K1 and PLK1 share more similar profiles, which indicates that the inhibition of these targets has specific effects on the in vitro viability and proliferation of cancer cells." (PMID 33795761, 2021). "In our study, we found that blocking TGF-β1 and vimentin deletion induced cancer cells to detach and survive, suggesting that PERK, PI3K/AKT, and ERBB2 may also be involved in the survival of detached cells through increasing the anoikis-independent process." (PMID 34830801, 2021). "Although most clinical focus has been on EGFR and ERBB2 due to their aberrant activation in many human malignancies, overexpression of ERBB3 often co-occurs with EGFR or ERBB2 in many types of cancers such as breast, colorectal (CRC), gastric, ovarian, and pancreatic." (PMID 34843459, 2021). "Moreover, ST6GAL1 endows resistance of cancer cells to gefitinib (EGFR inhibitor) and trastuzumab (anti-ErbB2 antibody) and also predicts the sensitivity of lenvatinib treatment to patients with hepatocellular carcinoma." (PMID 34745942, 2021). "As data for ERBB2 status were not collected by cancer registries until 2010, we restricted this analysis to 2010 to 2016, the most recent years for which more complete data were available." (PMID 32804214, 2020). "The overexpression of HER2 through HER2 (ERBB2) gene amplification or transcriptional deregulation plays important roles in many cancer types, including non-IBC and IBC." (PMID 32883032, 2020). "Moreover, the ErbB2 targeting antibody, trastuzumab (Herceptin), inhibits glycolysis via downregulation of HSF1 and LDH-A in ErbB2-positive cancer cells." (PMID 32219096, 2020). "As TOP2A gene is located adjacent to the ERBB2 gene, it is frequently either co-amplified with or independent of ERBB2 in many cancer types, including UCB43." (PMID 33298978, 2020). "In order to study the interplay of ErbB2 and actin filaments in membrane ruffles, we applied correlative fluorescence microscopy (FM) and liquid phase scanning transmission electron microscopy (STEM) of whole cancer cells." (PMID 32714928, 2020). "Alteration of the erythroblastic leukemia viral oncogene homolog (ErBb) family of the receptor tyrosine kinases (RTK) epidermal growth factor receptor (EGFR; also called ERBB1), ERBB2, ERBB3, and ERBB4 by comprehensive genomic or proteomic profiling has been identified in various cancer patients." (PMID 32708604, 2020). "Upon ERBB3 ligand binding and subsequent hetero-dimerization with ERBB2, diverse signaling pathways may be activated, such as the PI3K/AKT pathway, which is heavily involved in promoting chemoresistance in many cancers." (PMID 31164954, 2019). "The alterations in ERBB2 and WNT signaling overlap extensively with the pathways in cancer." (PMID 31248446, 2019). "Moreover, cosilencing of ERBB2 co-amplified genes, including ERBB2 and GRB7, results in increased apoptosis in cancers." (PMID 31083325, 2019).
cancer (continued). "ERBB2 amplification was often mutually exclusive with canonical oncogenic alterations in GC (83.3%; 5/6) and CRC (60%; 3/5) cancer patients, reinforcing its likely importance in these cancer types." (PMID 31019892, 2019). "ERBB2 is expressed in other cancer types, such as BLCA and CESC, which could benefit from repurposing and further exploration of HER2-inhibition; HER-2 inhibitors for COADREAD are currently being explored in late-stage clinical trials." (PMID 30053901, 2018). "Amplification of many RTKs occurs in a variety of human cancers, such as EGFR, ERBB2 and MET." (PMID 29455648, 2018). "Although ERBB2 is recognized as driver gene for several cancer types, but it is not curated as GBM driver gene in the two benchmarking lists." (PMID 29871594, 2018). "Increase in the copy number of ERBB2, a Tyrosine Kinase Receptor (TKR) leads to the overexpression of oncogene product and consequently uncontrolled cell proliferation which has been reported in different aggressive cancers with mitochondrial malfunctions." (PMID 29743853, 2018). "Third, given the prevalent incidence of upregulated CIP2A and Akt in various cancers, our understanding of CIP2A and lapatinib resistance may also shed light on the mechanisms of the resistance to other ErbB2-targeting drugs, such as trastuzumab." (PMID 28938602, 2017). "These segments contain known cancer genes including MYC, EGFR, ERBB2 CDKN2A, RB1 and STK11." (PMID 28686671, 2017). "Nevertheless, alterations in proto-oncogene pathways and tumor suppressor genes, including ERBB2/HER2, CD340, MLN19, NGL, NEU, and TKR1 may be involved in many types of human cancers." (PMID 29515634, 2017). "Trastuzumab did not down-regulate ERBB2 protein expression in ERBB2 overexpressing cancer cell lines." (PMID 28101782, 2017). "A dual inhibitor of both EGFR and ErbB2 tyrosine kinases activity, lapatinib, had been applied mainly in metastatic breast cancer, since in other types of cancer it did not act as an effective inhibitor of the phosphorylation." (PMID 28286519, 2017). "Moreover, team led by Dihua Yu has shown that ErbB2 (HER-2) increases VEGF protein production by activating S6K in cell lines, xenografts and in human cancers." (PMID 27154770, 2017). "Such interaction would give metastatic ErbB2-positive cancer cells a framework for them to survive without ECM attachment." (PMID 28306722, 2017). "In our data, and that of others, ERBB2 was down-regulated by trastuzumab in cardiomyocytes but not in ERBB2 overexpressing cancer cell lines." (PMID 28101782, 2017). "Four post-treatment cancers also showed focal copy number gains of ERBB2, CCND2, TERT and CCNE1 that were absent from the pre-treatment samples." (PMID 27045317, 2016). "Careful cell biological studies have revealed the lysosomal targeting of ErbB2 upon HSP90 inhibition to be a relatively early event, and one likely to be important for the rapid downregulation of ErbB2 from the surface of HSP90 inhibitor-treated cancer cells." (PMID 26859680, 2016). "For ERBB2, several studies indicated that ERBB2+ MBC patients have EMT-like CTC and that ERBB2 seems to be selectively expressed in cancer stem cells of initially ER+ and ERBB2-negative luminal BC." (PMID 27223437, 2016). "The location of the primary tumor, age, sex, histology of cancer cells, presence of lymphatic/perineural invasion, KRAS and BRAF mutation, or EGFR and ERBB2 expression did not significantly influence the success of PDC establishment." (PMID 26909603, 2016).
cancer (continued). "The objectives of this study were to determine the sequence of events leading to ERBB2 degradation upon HSP90 inhibition, to understand the mechanism of action of potentially useful anti-cancer drugs, and to better understand the biology of the role of HSP90 in the homeostasis of ERBB2." (PMID 27863425, 2016). "An ErbB2 overexpressing transgenic mouse exhibits increased numbers of LPC-like cells in the liver, and increased expression of ErbB family members is reported in a high proportion of human HCCs and correlates with cancer progression." (PMID 27777588, 2016). "In cancer cells and Schwann cells, NRG-1 signals through erbB2 and erbB3 receptors." (PMID 27596278, 2016). "Instead, it inhibits the ErbB2-downstream MAPK signaling pathway, which may partially explain how this miRNA suppresses the malignant behaviors of cancer cells." (PMID 25950472, 2015). "Considering these reports, LL-37 can be associated with dual aspects of cancer progression via various receptors, such as epidermal growth factor receptor (EGFR), FRP2, ERBb2, P2X7, and GAPDH, or suppression via interaction with peptide-based factors and cancer membrane components." (PMID 26175965, 2015). "Although linage specific analysis in RNAi data excluded genes that are important drivers for multiple cancers as well as ESCC, such as ERBB2 and EGFR, through knockdown assays in ESCC cell lines and additional survival analysis, we confirmed GRB7 as a new driver gene in ESCC." (PMID 26465158, 2015). "It is known that MYC is a downstream effector of ERBB2 signaling, that MYC-amplification results in Aurora kinase- dependent growth, and that co-amplification of ERBB2 and MYC is a frequent event in cancer." (PMID 26018524, 2015). "On the other hand, these FISH signals were absent from normal breast tissue as well as ERBB2-type and triple-negative-type cancer tissues, all of which were ER negative." (PMID 25923108, 2015). "To test whether the anti-ErbB2 DVD-Ig proteins retained the cell proliferation inhibition activity of mAb1 and mAb2, we screened the eight DVD-Ig proteins in a panel of human cancer cell lines via cell proliferation assay." (PMID 24824849, 2014). "A similar strategy using designed ankyrin repeat proteins targeted to different epitopes on ERBB2 has shown a high potential for cancer treatment in vitro that did not rely on the addition of functional payloads." (PMID 25089830, 2014). "Because many receptor proteins (e.g., EGFR, PDGFRA, PDGFRB, ERBB2, and ERBB4) are typically located in the upstream of cancer-related signaling pathways such as proliferation, cell death, and cell cycle progression, mutations in these genes are likely critical to cancer development." (PMID 24516372, 2014). "The malignant tumors displayed a significantly higher module score than the benign and borderline tumors for the AURKA/proliferation, STAT1/immune response, CASP3/apoptosis, VEGF/angiogenesis and ERBb2/HER2 signaling modules." (PMID 25226589, 2014). "WT1, KDR and ERBB2 may drive the carcinogenesis of GBM, indicating that CoMDP can identify low-frequency candidate driver genes that play important roles in cancer initiation and development." (PMID 25106096, 2014). "HIF1A mRNA is highly expressed in both basal and ERBB2 subtypes compared to luminal subtypes, in agreement with the observation that HIF1A protein is expressed at higher levels in basal cancers relative to luminal cancers." (PMID 25069832, 2014). "For example, the BioCarta ERK pathway consists of 28 genes including EGFR, IGF1R, and other receptor tyrosine kinases (RTKs) while the well established cancer genes ERBB2/3/4 are not included in the pathway." (PMID 23760067, 2013). "Although a number of strategies targeting erbB2 are being used in the clinic, no erbB3-targeted therapy has been approved for cancer treatment." (PMID 24168763, 2013).
cancer (continued). "Despite robust preclinical and encouraging clinical data in various cancer types, a third class of antineoplastic agents active against ERBB2, HSP90 inhibitors, has still not been approved by the FDA." (PMID 23630663, 2013). "(ErbB3: cancer tissues 3264±1032 vs. normal colorectal tissues 1038±354, P = 0.0074, ErbB2: cancer tissues 2616±2019 vs. normal colorectal tissues 338±154, P = 0.016, c-MET: cancer tissues 3812±739 vs. normal colorectal tissues 978±313, P = 0.0057 by Mann-Whitney U test)." (PMID 24205104, 2013). "For experimental validation, we selected cancer cell lines that harbor amplifications of ERBB2 (OE19) and FGFR2 (HSC39), and used cell lines without these amplifications as controls." (PMID 23737949, 2013). "An emerging consensus is that α6β4 complex synergizes with specific molecules such as ErbB2, EGFR, Ron, Fyn, c-Met, protein kinase C, CD151, and CD9 to activate key signaling pathways for the invasion and migration of carcinoma cells via activation of signaling molecules such as PI3K." (PMID 24015244, 2013). "Hsp90 has, in addition to ErbB2, a number of other client proteins, including Akt, that control cell growth, and GA-derivatives such as 17-allylamino-17-demethoxygeldanamycin (17-AAG) are currently in development for cancer treatment." (PMID 24281706, 2012). "Indeed, a previous study has revealed a role of cancer cell-expressed ADAMTS1 in metastasis with a mechanism involving activation of epidermal growth factor receptor and ErbB-2 and shedding of amphiregulin and heparin-bound epidermal growth factor precursors." (PMID 22514714, 2012). "Indeed, treatment of EGFR-positive cancer cells with CL4 strongly inhibits both the EGF-induced tyrosine phosphorylation of EGFR and ErbB2 and the Hrg-dependent tyrosine phosphorylation of EGFR and ErbB3." (PMID 21915281, 2011). "It is, therefore, not surprising that erbB2 has been the target of immunotherapy by monoclonal antibodies (mAb) in a number of cancers." (PMID 21876697, 2011). "Clinical assessment of ERBB2 and EGFR amplification may represent an important factor for the development of personalized treatment programs for gastic cancer." (PMID 21689422, 2011). "PTK6 may promote human cancer growth by modulating signaling via growth factors receptors, such as IGF-1R and ErbB2." (PMID 20668531, 2010). "Within luminal A ER+ (low-grade ER+) cases and patients with ERBB2+/ER- cancers, the GIPC1 signature was not predictive of recurrence-free survival." (PMID 21209904, 2010). "When we studied TXNRD1 expression in ERBB2-status-positive versus ERBB2-status-negative carcinomas, significantly higher levels were obtained for ERBB2-status-positive tumors in all three individual study cohorts." (PMID 20584310, 2010). "Cancer cells which respond to βGBP according to this pattern are non-invasive, non-aggressive cells with low levels of ErbB2." (PMID 19133120, 2009). "The approach of inhibiting IGF1R with a small molecule is validated by the numerous receptor tyrosine kinases (RTKs) that have been effectively targeted in the treatment of cancer, including Bcr-Abl (imatinib), EGFR (erlotinib, gefitinib) and EGFR/ErbB2 (lapatinib)." (PMID 19732452, 2009). "Despite these advances, the clinical benefit of Herceptin is compromised by the fact that not all ErbB2-overexpressing cancers respond clinically to the treatment and some cancers develop resistance to this molecularly targeted drug after initial response." (PMID 17426702, 2007). "Similarly, other benign variants such as ERBB2 p.Ile655Val, and KIT p.Met541Leu were identified in the present study, suggesting no pathogenic effect despite being located in cancer-related genes." (PMID 40725233, 2025). "ERBB2 amplification was most prevalent in GEC (15.5%), salivary gland (11.8%), bladder (10.9%), uterine (10.3%), and breast (9.9%) cancers, whereas ERBB3 amplification was most prevalent in small bowel (2.4%), uterine (2.2%), GEC (1.9%), biliary tract (1.5%), and ovarian (1.2%) cancers." (PMID 40178042, 2025).
cancer (continued). "This indicated that ERBB2 downstream pathway in canine iUC relied on the PI3K/AKT pathway, although ERBB2 could regulate multiple downstream pathways, such as MAPK and SRC, in human cancers." (PMID 40966256, 2025). "Specifically, we focused on four previously-studied, targeted anti-cancer drugs for which our model includes primary targets and significant off-targets: trametinib (MEK inhibitor), alpelisib (PI-3Kα inhibitor), neratinib (EGFR/ErbB2/ErbB4 inhibitor), and palbociclib (CDK4/6 inhibitor)." (PMID 40880521, 2025). "Conversely, we found no loss of ERBB2, EGFR, ABL1, RELA, and RELB transcript in c-MYC-destabilized cells compared to controls, and the 3′UTRMYC1-18-treated cancer cells tended to restore MYC expression towards the normal female mammary epithelial expression levels." (PMID 39123391, 2024). "During cancer progression, majority of cancer cells were putatively clones of minority by MET exon 14 clones, with diminished clones with FGF-FGFR or WNT, ERBB2, MAPK pathways, which may lead less FGFR-Activated or Bypass-Activated subtype in more advanced disease stages." (PMID 39060379, 2024). "The histopathological diagnosis was tubular 2, moderately differentiated cancer (Union for International Cancer Control classification, 7th edition), and ERB-B2 receptor tyrosine kinase 2-negative, tubular, moderately differentiated cancer (the World Health Organization classification of 2019)." (PMID 39165681, 2024). "Among central nodes were ERBB2 (v-erb-b2 avian erythroblastic leukemia viral oncogene homolog 2), CRK (Cysteine-rich receptor-like-kinase), HRAS, and KRAS (Kirsten rat sarcoma virus), all of which were proto-oncogenes involved in the development of various cancer types." (PMID 38304545, 2024). "However, when each special type was separately analyzed, ERBB2-low was less often found in mucin-producing carcinomas (pure mucinous or mixed with micropapillary) vs nonmucinous tumors (15 of 39 patients [38.5%] vs 1244 of 2161 patients [57.6%]; P = .02)." (PMID 38517439, 2024). "Indeed, Schettini and collaborators found higher levels of ERBB2 mRNA in H2L than in HER2-negative HR+ carcinomas, with higher levels in 2+ H2L carcinomas than in 1+ H2L carcinomas." (PMID 38893129, 2024). "HER2 is part of the epidermal growth factor receptor (EGFR/Erb) family of tyrosine kinase receptors, which consists of four members-EGFR/HER1/ErbB1, HER2/ErbB2, HER3/ErbB3, and HER4/ErbB4-and is closely related to cell proliferation, differentiation, migration, and cancer development." (PMID 36937848, 2023). "Fourth, approximately 62% of the patients with ERBB2+ cancer had missing values in the ERBB2/CEP17 ratio, so patients with these data available might not be representative, which limits the external generalizability of our findings on the ERBB2/CEP17 ratio." (PMID 36995711, 2023). "In addition, plexins have been shown to couple with transmembrane tyrosine kinases of the receptor type such as ErbB2 and Met, thereby triggering alternative noncanonical signaling cascades, especially in cancer cells." (PMID 36722641, 2023). "From our results, we hypothesized the following combination algorithm: a decrease in cfDNA level, normal ERBB2 copy number, and absence of TERT C228T mutations after drug therapy indicate the suppression of cancer (PR)." (PMID 37945655, 2023). "For example, there were no data on whether a patient with ERBB2+ cancer received trastuzumab or pertuzumab." (PMID 36995711, 2023).